S100A12 (S100 calcium binding protein A12)
Diseases named in the same sentence as S100A12 in open-access papers (continued):
Sharing a sentence is not in itself a finding about the gene and the disease.
diabetes (15 papers, 2009 to 2025). "Studies have demonstrated that serum S100A12 levels were elevated in T1D patients, and such elevations were associated with inflammatory responses and diabetes in patients with stage 5 chronic kidney disease (CKD)." (PMID 39040677, 2024). "Previous studies have suggested that higher S100A12 levels in patients with diabetes accelerate the development of PAD in patients, ultimately advancing the event of amputation." (PMID 40269701, 2025). "The area under the curve (AUC) values for S100A12, IL1R1, and FCGR2B were 0.744, 0.785, and 0.868, respectively, indicating robust diagnostic efficacy for diabetes-associated IDD." (PMID 41169383, 2025). "Univariate logistic regression analyses revealed that diabetes and plasma S100A12 levels were promotive factors for PAD, whereas HDL-C levels were protective factors for PAD." (PMID 40269701, 2025). "The results of the subgroup analyses suggested that S100A12 was positively associated with the risk of PAD in all subgroups grouped by HDL-C, hypertension, diabetes, and age." (PMID 40269701, 2025). "By univariable analysis advanced age, male sex, Killip class, diabetes, history of stroke, treatment with angiotensin-converting enzyme inhibitors (ACEI) and statins at discharge, peak S100A12 level were associated with 1-year MACCE." (PMID 34977174, 2021). "Few studies have evaluated the effect of diabetes on the sRAGE and S100A12 levels in patients with CAD." (PMID 31275446, 2019). "The serum levels of S100A12 in RA patients in MLR analysis were positively associated with ACPA, a history of diabetes, and serum levels of S100A9 (P < 0.05)." (PMID 19284577, 2009). "In simple linear regression analysis, the serum levels of S100A12 in RA patients were positively associated with ACPA, RF, history of diabetes, and serum levels of S100A8 and S100A9 (P < 0.05)." (PMID 19284577, 2009). "Diabetes, elevated hscTnT and symptom onset time were more common in patients with high plasma S100A12 levels; other baseline characteristics were unrelated to S100A12." (PMID 34977174, 2021). "In 199 patients on hemodialysis in whom vascular calcium scores were obtained (49.2% of the subjects had diabetes), circulating levels of sRAGE were negatively associated with calcium score independent of the level of S100A12 and inflammatory markers." (PMID 32211423, 2020). "The plasma concentration of S100A12 in patients with diabetes was two-fold higher than in controls." (PMID 25110868, 2014). "S100A12 levels were associated with presence of ACPA, history of diabetes, and serum S100A9 levels." (PMID 19284577, 2009). "Further subgroup analyses showed that the positive association between S100A12 and the risk of PAD was significant in all subgroups, regardless of whether HDL-C levels were less than 1.03 mmol/L, age greater than 60 years, and presence of diabetes or hypertension." (PMID 40269701, 2025). "Full length (fl)RAGE, soluble (s)RAGE, endogenous soluble (es)RAGE, S100A12 (enRAGE) and advanced-glycation-end-products (AGE) expression was assessed in serum, white blood cells and sputum of patients with CF; diabetes; CFRD and healthy subjects." (PMID 25754382, 2015). "S100A12 acts as a pro-inflammatory agent in vivo, with a close relationship with plaque formation in patients with acute coronary syndrome (ACS), end-stage renal disease, and diabetes." (PMID 40269701, 2025). "However, comparable levels of PECAM1, CXCR2, SLC2A3, BST2, S100A11, S100A12, and CPNE3 were found in neutrophils from diabetes patients and controls (P > 0.05)." (PMID 32377527, 2020). "Therefore, in the present study, we attempted to determine the expression of sRAGE and S100A12 and their relationship in the subjects with different severity levels of CAD, and we also attempted to evaluate what influence diabetes has on them." (PMID 31275446, 2019).
periodontitis (15 papers, 2015 to 2025). An acute or chronic inflammatory process that affects the tissues that surround and support the teeth. "Neutrophil-driven responses, particularly involving S100A12, have been implicated in the pathogenesis of periodontitis by mediating both local and systemic inflammatory processes." (PMID 40462074, 2025). "According to our knowledge, there are no other previous studies on the association between genetic polymorphisms of S100A8, S100A9, or S100A12 and periodontitis." (PMID 35315933, 2022). "The present study investigated S100A12 dynamics in monocyte subsets, during monocyte maturation stages and polarization, as well as its association with periodontitis." (PMID 32082330, 2020). "Finally, GWAS studies of periodontitis found that S100A12 polymorphisms appear to influence periodontitis." (PMID 38098978, 2023). "In addition, one study with a higher risk of bias highlighted higher expression of S100A12 in patients with UC and chronic periodontitis." (PMID 34501547, 2021). "However, a significant increase in the proportion of S100A12+ MCs was found in periodontitis, and the periodontitis-associated S100A12+ MCs were less frequently CD206+, a marker of alternatively activated macrophages." (PMID 32082330, 2020). "The results provided genetic evidence for significant associations between genetically predicted levels of family Pasteurellaceae, 45 blood metabolites, and 4 inflammatory proteins (IL-4, IL-22RA1, S100-A12, TNFSF12) and periodontitis susceptibility." (PMID 41001956, 2025). "S100A8, S100A9, S100A12, were all elevated in saliva from periodontitis and gingivitis patients compared to healthy controls and salivary levels of S100A8, S100A9 and S100A12 were significantly related to clinical and radiographic signs of periodontitis." (PMID 38098978, 2023). "This altered level of S100A12, in both peripheral circulatory and gingival tissue monocytes, indicates its functional role in periodontitis pathogenesis." (PMID 35892571, 2022). "Regarding the local impact of periodontitis, previous research has shown that decreased levels of IL-4 and increased levels of MMP-8, PGE2 and S100A12 in the oral cavity are associated with higher periodontal deterioration." (PMID 34501547, 2021). "S100A12 levels were significantly increased in patients with more severe stages of periodontitis (III and IV) in comparison with healthy/gingivitis participants." (PMID 32082330, 2020). "In consonance with the increased expression of S100A12 in peripheral monocytes in periodontitis, we also found higher expression of S100A12 as well as increased frequency of S100A12+ monocyte-derived cells in gingival tissue affected by periodontitis." (PMID 32082330, 2020). "Peripheral monocytes from periodontitis patients had higher S100A12 expression than monocytes from controls, a difference particularly observed in the intermediate and non-classical monocyte subsets." (PMID 32082330, 2020). "Further, monocytes from periodontitis patients displayed an increased secretion of S100A12 compared with monocytes from controls." (PMID 32082330, 2020). "This study implicates the involvement of S100A12 in the pathogenesis of periodontitis, and both gingival tissue and circulatory monocytes are altered in periodontitis." (PMID 32082330, 2020). "After 24 h in culture, monocytes from periodontitis patients secreted significantly higher levels of S100A12 than control monocytes." (PMID 32082330, 2020). "Western blot evaluation of tissue protein extracts revealed a significantly higher expression of S100A12 in periodontitis compared to controls." (PMID 32082330, 2020). "Further, we explored the involvement of S100A12 in periodontitis by analyzing its expression in peripheral circulation and gingival tissue, as well as in saliva." (PMID 32082330, 2020). "Further, S100A12+ monocyte-derived cells (MCs) in gingival tissue from periodontitis patients and controls were characterized." (PMID 32082330, 2020).
periodontitis (continued). "The monocytes from periodontitis patients also secreted significantly higher levels of S100A12 after 24 h in monoculture than monocytes from periodontally healthy participants." (PMID 32082330, 2020). "Further, we aimed to explore its involvement in periodontitis using a 3D co-culture tissue model, and by analyzing S100A12 expression in tissue, peripheral circulation, and saliva from patients with periodontitis." (PMID 32082330, 2020). "Immunohistochemical analysis showed strong S100A12 staining in the connective tissue mainly in conjunction with the inflammatory infiltrate in periodontitis, whereas in the controls a weak staining was seen in the connective tissue." (PMID 32082330, 2020). "Patients having periodontitis stages I and II exhibited a tendency toward higher S100A12 levels than the healthy/gingivitis individuals (p = 0.06)." (PMID 32082330, 2020). "Since inflammatory stimuli modulates S100A12 levels in oral tissue cultures, the expression of S100A12 in gingival tissue affected by periodontitis was evaluated." (PMID 32082330, 2020). "Activity of S100A12 and C-reactive protein can be markers of inflammatory activity in chronic periodontitis." (PMID 26251029, 2015). "(D) Regional Manhattan plot of conditional analysis for S100A9, S100A12 in periodontitis." (PMID 38536078, 2024). "The high-confidence genes S100A9 and S100A12, located on 1q21.3, could potentially serve as immunomodulatory targets for neutrophil-mediated periodontitis." (PMID 38536078, 2024). "Notably, four of these high-confidence genes were found to be involved with multiple phenotypes: S100A9, S100A12 (neutrophils and periodontitis); MCM6, P14KAP2 (neutrophils and pDC)." (PMID 38536078, 2024). "The S100A12 gene was a significant DEG in gingival tissues of periodontitis." (PMID 38098978, 2023). "In addition, another study showed that circulating monocytes from periodontitis patients had an altered expression of S100A12, suggesting its involvement in the pathogenesis of periodontitis." (PMID 37224160, 2023). "Salivary S100A8, S100A12, and MMP‐8 concentrations were associated with periodontitis, ABL, the number of periodontal pockets with PPD 4 to 5 mm, and especially the number of periodontal pockets with PPD ≥ 6 mm (OR for 10‐fold increase in S100A8: 4.22; 95% CI, 2.15 to 8.30; P < 0.001)." (PMID 35315933, 2022). "However, saliva levels of S100A8, S100A12, MMP‐8, and TCC, and CFH polymorphisms were associated with clinical and radiographic signs of periodontitis." (PMID 35315933, 2022). "We investigated whether the polymorphisms linked to serum MMP‐8 associate with periodontitis, periodontal parameters, and saliva concentrations of TCC, S100A8, and S100A12 in a well‐characterized, relatively large sample of middle‐aged or elderly participants." (PMID 35315933, 2022). "Although the measured saliva concentrations of TCC, S100A8, and S100A12 were significantly higher in periodontitis, the corresponding genetic polymorphisms did not correlate with the saliva levels." (PMID 35315933, 2022). "Therefore, the increased salivary levels of S100A12 in patients with UC and periodontitis deserves to be further explored." (PMID 34501547, 2021). "S100A12 levels in saliva reflect the severe stages of periodontitis." (PMID 32082330, 2020). "Moreover, in a 3D oral tissue culture inflammatory stimuli modulated S100A12 expression in the presence of monocytes, and the frequency of S100A12+ monocyte-derived cells was increased in inflamed gingival tissue affected by periodontitis." (PMID 32082330, 2020). "Levels of S100A12 in saliva were higher in patients with severe stages of periodontitis." (PMID 32082330, 2020). "Likewise, S100A12 expression was higher in gingival tissue from periodontitis patients where monocyte-derived cells exhibited higher expression of S100A12 in comparison to non-periodontitis tissue." (PMID 32082330, 2020).
periodontitis (continued). "As S100A12 gene expression is very sensitive to low levels of LPS, we speculate that higher exposure to LPS in periodontitis might be at least partially responsible for the enhanced S100A12 expression seen in this study." (PMID 32082330, 2020). "The percentage of S100A12+ monocytes was higher in periodontitis than in controls." (PMID 32082330, 2020). "Peripheral monocytes from periodontitis patients showed altered expression of S100A12." (PMID 32082330, 2020). "This study implicates the involvement of S100A12 in periodontitis pathogenesis, as evidenced by increased S100A12 expression in inflamed gingival tissue, which may be due to altered circulatory monocytes in periodontitis." (PMID 32082330, 2020). "Additionally, S100A12 expression is modulated by monocytes in periodontitis." (PMID 35892571, 2022). "S100A12 was also found to be increased in GCF and serum of CP patients and even more elevated in T2DM patients with periodontitis." (PMID 38098978, 2023). "Among the studied polymorphisms of CFH, MMP8, and S100A8/S100A9/S100A12 gene region, those located in the CFH gene associated with periodontitis, whereas the ones near S100A9 or in the MMP8 gene did not." (PMID 35315933, 2022). "In periodontitis, S100A12 expression is higher in classical monocytes than in non-classical monocytes." (PMID 34148033, 2021). "Furthermore, S100A12+ cells in periodontitis showed a lower expression of CD206 than in controls, and the percentage of S100A12+ cells correlated negatively with that of CD206+ cells." (PMID 32082330, 2020). "In comparison to healthy controls, a greater proportion of intermediate and non-classical monocytes from periodontitis patients were S100A12+." (PMID 32082330, 2020). "In line with our findings, patients with severe periodontitis had significantly higher levels of S100A12 in saliva compared to non-periodontitis patients, and the levels correlated to clinical periodontal parameters." (PMID 32082330, 2020). "Interestingly, results showed an up-regulation of colony-stimulating factor-1 (CSF-1), S100A8/A9, S100A12, interleukin (IL)-1β, matrix metalloproteinase (MMP)-8, and hepatocyte growth factor (HGF), in patients with periodontitis with a statistical significance of p<0.001." (PMID 37224160, 2023). "Also, S100A12 levels were significantly higher in patients having periodontitis stages III and IV than in non-periodontitis participants." (PMID 32082330, 2020). "Interestingly, we found that circulating monocytes from periodontitis patients have an altered expression of S100A12, which was mainly seen in the intermediate and non-classical subsets." (PMID 32082330, 2020). "Salivary S100A12 was also elevated in both periodontitis and gingivitis groups compared to control groups, but no significant change was found in the levels of S100A8/A9 (calprotectin) and S100A12 after nonsurgical periodontal therapy." (PMID 35315933, 2022). "Higher expression of S100A12 was found in patients with UC with chronic periodontitis when compared to non-IBD and CD patients also with periodontitis." (PMID 34501547, 2021).
Kawasaki disease (14 papers, 2009 to 2024). A rare inflammatory disease characterized by an acute febrile, systemic, self-limiting, medium-vessel vasculitis primarily affecting children. "In patients with Kawasaki disease, or with chronic hyperglycemia, serum levels of S100A12 were inversely associated with serum levels of sRAGE." (PMID 19284577, 2009). "Our data is consistent with previous reports showing that S100A12 correlated with inflammatory activity in Kawasaki disease, an acute form of vasculitis." (PMID 30533405, 2018). "It has recently been confirmed that S100A12, as a highly expressed vector of aseptic inflammation in Kawasaki disease, may activate human coronary artery endothelial cells (hCAECs) in an IL-1 β-dependent manner." (PMID 37217870, 2023). "In 50 children with acute Kawasaki disease, sRAGE levels were decreased in patients with high disease activity and in non-responders after intravenous immunoglobulin treatment, being inversely correlated to S100A12." (PMID 26854151, 2015). "In addition, S100A12 may indicate the presence of a coronary artery injury in children with Kawasaki disease." (PMID 37217870, 2023). "Therefore, it is believed that the expression of S100A12 may indicate the presence of coronary artery injury in children affected by Kawasaki disease or may even be involved in the mechanism of coronary artery injury." (PMID 37217870, 2023). "Consistent with our findings, a study reveals that CM highly express S100A8, S100A9, and S100A12, IM express HLA-DQA1 and HLA-DPA1 and NCM mainly express CD16, demonstrating a distinct transcriptome across monocyte subsets in Kawasaki disease." (PMID 39318997, 2024). "Moreover, the monocyte marker genes S100A8 and S100A12 were enriched with larger weights on PANDA latent component 3 and were reported to exert proinflammatory functions in Kawasaki disease (KD) patients." (PMID 38798352, 2024).
asthma (13 papers, 2011 to 2025). "To explore the relationship among the levels of IL-4, IL-25, and S100A12 in nasal lavage fluid in patients with AR, asthma, and asthma comorbid AR, we performed Spearman correlation coefficient tests." (PMID 35348596, 2022). "In the lung, increased levels of S100A8, S100A9 and S100A12 have been found in asthma, cystic fibrosis, chronic obstructive pulmonary disease, idiopathic pulmonary fibrosis, acute respiratory distress syndrome and ventilator associated lung injury." (PMID 25706559, 2015). "Furthermore, S100A12 has been reported to induce mast cell activation and enhance allergic inflammation and asthma." (PMID 40929127, 2025). "In search of novel approaches in diagnosing and treating patients with asthma, S100A12, ratio AGE/sRAGE, and DJ-1 in addition to IL-6 may prove to be useful tools." (PMID 37371535, 2023). "Despite these limitations, the findings discussed here indicate that the AGEs-RAGE system and DJ-1 are closely related with the pathophysiology of asthma, and AGEs/sRAGE ratio, S100A12 and DJ-1 could serve as novel biomarkers to predict asthma treatment." (PMID 37371535, 2023). "In expression feature analyses, we observe universal upregulation of S100A8, S100A9, S100A12, and RETN in various cell types of asthma patients, particularly S100A8 and S100A9." (PMID 41550933, 2025). "S100A8, S100A9, S100A12, and RETN are universally upregulated in various cell types of asthma patients." (PMID 41550933, 2025). "However, mice overexpressing human S100A12 in lung SMC have reduced peribronchial and perivascular inflammation, mucus production, and eosinophilia following acute antigen challenge in asthma, indicating a protective effect." (PMID 23638054, 2013).